INS (insulin)
Diseases named in the same sentence as INS in open-access papers (continued):
Sharing a sentence is not in itself a finding about the gene and the disease.
Hypokalemia (continued). "Therefore, it is recommended to stop insulin administration for any patient who develops symptomatic hypokalemia until the potassium level is above 3.3 mM/L." (PMID 37605707, 2023). "However, the administration of potassium to correct hypokalemia has managed to normalize insulin secretion and glucose tolerance only partially." (PMID 37628857, 2023). "On the other hand, insulin shifts potassium back intracellularly, and patients might develop profound hypokalemia that occurs despite aggressive replacement." (PMID 37605707, 2023). "Insulin should be withheld if blood K+ is below 3.3 mmol/L to avoid insulin-induced hypokalemia." (PMID 35334607, 2022). "In individuals with DM, hypokalemia results from three different groups of events: transcellular shifts (particularly due to high dosages of insulin or as a result of metabolic acidosis), abnormal losses (gastrointestinal losses, renal losses, dialysis, or hypomagnesemia), or inappropriate intake." (PMID 35334607, 2022). "In this paper, we explore different originating conditions of hypokalemia—reduced potassium intake, increased excretion, acid-base disturbances, and increased insulin—by using a dynamic mathematical model for potassium balance in non-lactating and lactating cows." (PMID 36396697, 2022). "This phenomenon is well described, and severe hypokalemia necessitates delaying insulin therapy." (PMID 35494963, 2022). "During insulin treatment, plasma K+ levels will invariably fall, possibly leading to hypokalemia." (PMID 35334607, 2022). "Previous literature reported that hypokalaemia also inhibits insulin secretion." (PMID 35937831, 2022). "Similarly, very few studies provided information about the addition of potassium to the glucose/insulin infusion to avoid hypokalaemia and the potential arrhythmia-provoking consequences." (PMID 33566134, 2021). "This means the minor [K+]‐lowering glucose‐insulin effects at rest were greatly amplified under conditions of intense intermittent exercise and in early recovery, when [K+] fluctuated markedly between baseline, well above baseline and hypokalemia in recovery." (PMID 34110701, 2021). "All the major guidelines further acknowledge that insulin mediated reentry of potassium from extracellular to intracellular compartment may precipitate hypokalemia, and hence, insulin should be withheld if the serum level of potassium is below 3.3 mmol/L." (PMID 29619008, 2018). "Reintroduction of feeding induces insulin secretion, which facilitates the transport of plasma phosphate, potassium, and magnesium along with glucose into the cells, resulting in hypophosphatemia, hypokalemia, and hypomagnesemia." (PMID 29104345, 2017). "Studies have shown that hypokalaemia leads to impaired secretion of biologically active insulin, and insulin insensitivity due to unknown reasons." (PMID 28446151, 2017). "The larger amounts of glucose could stimulate insulin secretion, resulting in hypophosphatemia and hypokalemia." (PMID 29104345, 2017). "The role of low potassium (hypokalemia) in insulin secretion remains controversial." (PMID 28600547, 2017). "Thiazide diuretics have a common side effect of lowering serum potassium and evidence shows that diuretic-induced hypokalemia may lead to impaired glucose tolerance via reduction in insulin secretion in response to glucose loads." (PMID 27455317, 2016). "Increased catecholamine levels in response to stress of the infection and secondary insulin release may result in intracellular shift of potassium and hypokalaemia." (PMID 23530968, 2013). "Importantly, both hypomagnesemia and hypokalaemia can impair insulin secretion and sensitivity." (PMID 41751411, 2026). "Other concurrent environmental factors, such as hypokalemia, may impair insulin action." (PMID 40079488, 2025).
Hypokalemia (continued). "In addition to hypophosphatemia, hypokalemia, and hyponatremia, the biochemical investigations of the patient showed an increase in random glucose levels and a decrease in the levels of C peptide and insulin." (PMID 36140215, 2022). "However, whether patients with 17OHD, a characteristic of elevated mineralocorticoid hormone DOC levels and hypokalaemia, have insulin dysfunction and abnormal glucose metabolism remains unknown." (PMID 35937831, 2022). "No patients were given diuretics, bronchodilators, insulin, and other drugs that might cause hypokalemia." (PMID 32525548, 2020). "A glucose and insulin infusion causes potassium to move intracellularly, so the addition of exogenous potassium (glucose–insulin–potassium [GIK] infusion) helps to prevent hypokalaemia and to electrically stabilize the cardiomyocyte cell membrane to avoid arrhythmias." (PMID 31430831, 2020). "Routine outpatient insulin treatment does not cause significant hypokalemia." (PMID 33152003, 2020). "None of the dogs showed clinical signs associated with hypokalemia during insulin protocols." (PMID 33195532, 2020). "Thus, there might be a possibility that insulin-induced hypokalemia may enhance sodium inward current." (PMID 22567005, 2012). "In instances where hypokalemia occurred after CII was started, the serum potassium level at the start of treatment was significantly lower (p=0.003), and the insulin flow rate per body weight was significantly higher (p=0.013)." (PMID 40546498, 2025). "Furthermore, insulin-induced hypokalemia may mediate the role of insulin’s sodium-retaining effect." (PMID 39167349, 2024). "Although profound hypokalemia is uncommon with DKA, aggressive replacement is recommended, and insulin drip should be withheld when potassium levels are < 3.3 mEq/L." (PMID 39360087, 2024). "If serum hypokalaemia is present at the time of DKA diagnosis, potassium replacement should be initiated together with resuscitation fluids and the initial insulin infusion should be delayed." (PMID 37568965, 2023). "Whereas in the past a preventive potassium shift by glucose/insulin administration was often required, this should be omitted in HOPE-perfused livers to avoid hypopotassemia." (PMID 36555997, 2022). "In addition, when patients with thiazide-induced hypokalemia are given potassium supplements, the defects in insulin release in response to glucose loads are corrected, thus indicating that hypokalemia may be a significant contributing factor to the glucose abnormality." (PMID 27455317, 2016). "Hypokalemia is the second most common complication during treatment of DKA and HHS using insulin." (PMID 41141170, 2025). "Despite initial hyperkalemia (often seen in DKA), insulin therapy without potassium supplementation can precipitate life-threatening hypokalemia." (PMID 41141170, 2025). "Hypokalemia was also not different between the groups either during IV insulin (23%, p = 0.242) or within 12 h of IV insulin discontinuation (31%, p = 0.356)." (PMID 39136541, 2024). "Studies show that the probable mechanism of developing hypokalemia is increased insulin and catecholamine, but it is still not well-established." (PMID 39188452, 2024). "Recent studies have shown that the incidence of hypokalemia in DKA may be lower than 4%, appearing, in most cases, only after insulin administration." (PMID 35334607, 2022). "However, high doses of insulin, whether due to incorrect administration during the treatment of T1DM and T2DM in advanced stages or during the treatment of acute complications of DM, can lead to hypokalemia, which is the most common cause of low serum K+ concentrations in individuals with DM." (PMID 35334607, 2022). "Nevertheless, the use of high dose insulin, even with tight glycaemic control, would have to be approached with caution in SAP patients in critical care, given the potential problems of ketoacidosis, hypokalemia or other metabolic disturbances." (PMID 34282152, 2021).
Hypokalemia (continued). "No patients developed hypokalemia with SZC, despite a potentially increased risk while concomitantly receiving insulin and glucose." (PMID 32149451, 2020). "Upon resolution of her acidemia, the patient was transitioned from insulin infusion to treatment with a subcutaneous insulin aspart and insulin detemir, and did not experience further hypokalemia." (PMID 31485356, 2019). "Monitoring and correcting potassium levels is critical before insulin administration, as insulin drives potassium into cells and may precipitate life-threatening hypokalemia if not addressed." (PMID 41149081, 2025). "Hypokalemia in TPP occurs due to a massive shift of potassium into the cells, which has been linage to excess thyroid hormone, which has a synergistic effect with epinephrine or insulin, and therefore, increasing Na+/K+‐ATPase activity leads to potassium shift into the cells, as seen in our patient." (PMID 37197293, 2023). "Although hypokalemia which develops during DKA rarely becomes symptomatic, the results of the present study supports the use of potassium supplementation from the 1st h of insulin therapy, but only if urinary production is adequate and frequent assessments of the kalemia are possible." (PMID 33195532, 2020). "Moreover, a moderate potassium depletion, which did not induce frank hypokalemia, was proven to decrease plasma insulin concentrations and to induce resistance to insulin action." (PMID 23372822, 2013). "Notably, non-diabetic rats are noted to have diverse rates of insulin-induced mortality, ranging from 14%–47%, that may be attributed to variability in hypokalemia, neuroglycopenia, or sympathoadrenal responses that were not assessed in this analysis." (PMID 37200277, 2023).
lipodystrophy (179 papers, 2007 to 2026). A congenital or acquired disorder characterized by abnormal loss or redistribution of the adipose tissue in the body. "Another important aspect of appropriate insulin administration is the rotation of sites to reduce the risk of insulin-induced lipodystrophy, including lipohypertrophy and lipoatrophy." (PMID 40376558, 2025). "The potential therapeutic targets for ASO and siRNA include genes involved in adipocyte differentiation, lipid metabolism, insulin sensitivity and inflammatory processes, as well as those linked to specific mutations in lipodystrophy-associated genes." (PMID 39944202, 2025). "Here, we show that serine protease inhibitor A1 (SerpinA1) expression in the liver is increased during recovery from lipodystrophy caused by the adipocyte-specific loss of insulin signaling in mice." (PMID 39532838, 2024). "It is well known that insulin plays a crucial role in both adipogenesis and lipogenesis, and the deletion of the constitutive insulin receptor (IR) in adipocytes causes lipodystrophy." (PMID 37834368, 2023). "Other drugs, such as insulin, penicillin, injectable steroids, have been implicated in the development of localized lipodystrophy or bullous reactions followed by local dystrophy and difficult local treatments." (PMID 37600771, 2023). "Although patients attending our Diabetes Centre and their caregivers are routinely educated to rotate insulin administration sites, some subjects disregard this clinical recommendation, resulting in high susceptibility to onset of lipodystrophy." (PMID 35884071, 2022). "Altogether, these data support that seipin deficiency in adipocytes leads to lipodystrophy that induces liver steatosis and liver insulin resistance." (PMID 35054926, 2022). "Improper rotation of insulin administration sites and low awareness on lipodystrophy were associated to the occurrence of this skin condition (p = 0.050 and p = 0.005, respectively)." (PMID 35884071, 2022). "Several experimental studies have identified lipodystrophy as a cause of impaired insulin absorption." (PMID 35884071, 2022). "A significant association between improper rotation of insulin administration areas and presence of lipodystrophy was found (p = 0.050)." (PMID 35884071, 2022). "A rare complication of the use of insulin-injection treatment is lipodystrophy, where the repeated injection of insulin at the same site causes the subcutaneous fat to be damaged and take a retracted scar shape." (PMID 36361131, 2022). "Previously, loss of ARL15 was shown to reduce insulin secretion in a human β-cell line and loss-of-function mutations are found in some lipodystrophy patients." (PMID 34779483, 2021). "A multivariate analysis revealed a positive association between occurrence of lipodystrophy and errors in insulin injection technique, such as improper rotation of needle at the site of injection and inappropriate spacing between insulin doses." (PMID 33133845, 2020). "The prevalence of insulin-induced lipodystrophy was 58.5%, in which lipohypertrophy accounted for 97.1% of the lipodystrophy variant and the rest (2.9%) was lipoatrophy." (PMID 30116742, 2018). "Mechanistic study revealed that deficiency of HSL in adipose tissue caused inflammatory macrophage infiltrates, progressive lipodystrophy, abnormal adipokine secretion and systemic insulin resistance." (PMID 29232702, 2017). "This raises the possibility that AKT2 is more important for insulin action in adipocytes than in hepatocytes, so that partial loss of its function is expressed as a predominantly “lipodystrophy-like” metabolic phenotype." (PMID 27766312, 2016). "Incidentally, ‘buffalo hump’ is also present in HIV-associated lipodystrophy after prolonged use of protease inhibitors, and is associated with overall state of insulin resistance." (PMID 26599361, 2015). "Subject 1 was a boy with brittle diabetes and lipodystrophy in insulin injection sites associated to the presence of IA." (PMID 24386337, 2013).
lipodystrophy (continued). "Humans harboring loss of function PPARγ mutation (P467L) show a pattern of lipodystrophy and are insulin resistant." (PMID 22168210, 2011). "Drug-induced lipodystrophy at the site of injection has been associated with insulin therapy." (PMID 40565151, 2025). "Moreover, AT also partially reversed lipodystrophy-induced inhibition of insulin sensitivity-associated gene expression in both the livers (Irs2 and Akt2) and the skeletal muscles (Akt2) of Seipin/Apoe dKO mice." (PMID 38525541, 2024). "The lipodystrophy cluster comprises index SNVs for which T2D risk alleles are associated with increased fasting insulin, WHR, blood pressure and triglycerides, and with decreased body fat percentage, gluteofemoral adipose tissue (GFAT) volume and HDL cholesterol." (PMID 38374256, 2024). "Likewise, several clinical features, such as younger age, lower BMI, and higher daily insulin dose, have been demonstrated as factors associated with increased lipodystrophy risk in other studies." (PMID 39691127, 2024). "We show that primary IR, whether caused by proximal defects in insulin signaling or lipodystrophy, is sufficient to cause ovarian hyperandrogenism with ovarian morphology indistinguishable from common PCOS." (PMID 33901270, 2021). "Interestingly, one hallmark of ID patients and ID mouse models are metabolic problems, for instance altered adiposity and lipodystrophy and alterations in insulin sensitivity and EE43, all processes closely linked to brown and WAT (dys)-function." (PMID 30190464, 2018). "However, some patients still present relatively high IA titer levels, frequently associated with brittle diabetes, lipodystrophy in injection sites and/or poor metabolic control despite the high insulin doses administered." (PMID 27617231, 2016). "It is well known that other drugs such as insulin, antibiotics and methothrexate could also cause localised lipodystrophy in the injection site." (PMID 23226250, 2012). "The underlying mechanism for this lipodystrophy might be due to mitochondrial toxicity and insulin resistance." (PMID 22479575, 2012). "This study also importantly highlights the differences in insulin site rotation and lipodystrophy awareness on lipodystrophy." (PMID 40003213, 2025). "Conversely, autoimmune conditions and the use of certain medications, such as HIV antiretrovirals, corticosteroids, checkpoint inhibitors and insulin, can suggest acquired forms of lipodystrophy." (PMID 40892266, 2025). "Due to severe insulin resistance, many patients with lipodystrophy require large doses of insulin to control their blood glucose levels." (PMID 40892266, 2025). "Insulin-induced lipohypertrophy (LH) is a localized lipodystrophy that results from repeated subcutaneous injections at the same site." (PMID 40003213, 2025). "An important topic with which the participants expressed unfamiliarity was the proper steps to avoid lipodystrophy during insulin administration." (PMID 40008736, 2025). "Beyond the absence of adipose tissue, it is important to note that Seipin−/− mice also exhibit severe fatty liver and insulin resistance—well‐established features of lipodystrophy." (PMID 39980067, 2025). "In-person physical examination is also necessary, as lipodystrophy assessment and technique retraining can improve HbA1c and daily insulin use." (PMID 40003213, 2025). "Lipodystrophy is one of the most significant dermatological issues seen in areas receiving insulin injections and can lead to serious skin problems like chronic suppurative infections." (PMID 41268161, 2025). "Lipodystrophy is a condition marked by abnormal fat distribution at insulin injection sites; it is not only a physical complication of insulin therapy, but it can also lead to significant psychological distress." (PMID 39759721, 2024).